GATA3 (GATA binding protein 3)
Diseases named in the same sentence as GATA3 in open-access papers (continued):
Sharing a sentence is not in itself a finding about the gene and the disease.
cancer (continued). "Importantly, GATA3 IHC is routinely employed to ascertain breast or urothelial origin in carcinomas of unknown primary." (PMID 39931207, 2024). "Indeed, our previous analysis of CK5-expressing (IHC defined basal-like) carcinomas demonstrated 82%, 30% and 23% positivity with any staining for GATA3, MGB and GCDFP-15, respectively, but this decreased to 23%, 12% and 9% by applying a cut-off as low as > 5% staining." (PMID 37012444, 2023). "Therefore, colossal heterogeneity existed in the expression profiles of GATA3 in pan-cancers." (PMID 35647011, 2022). "Other described transcription factors regulating LOX at the promoter level includes GATA-binding protein 3 (GATA-3)—which is also associated with T-helper 2 polarization—and the pro-survival transcription factor forkhead box M1b (FoxM1b), often over-expressed in cancer." (PMID 31650200, 2020). "In addition, GATA3 expression is correlated with longer disease-free survival and evidence suggests that it can prevent or reverse the epithelial to mesenchymal transition that is characteristic of cancer metastasis." (PMID 22951069, 2012). "The results showed that cancer cell marker genes, such as CDH1, EPCAM, FOXA1, and GATA3, were enriched within the spatial domain (sections (−120, −90], (−90, −60], (−60, −30] and (−30, 0])." (PMID 39965034, 2025). "GATA-3 was focally expressed in the SCCP tissue of this patient, and Ki-67 and p63 were concentrated in the nucleus of cancer cells in the cancer nest." (PMID 40746833, 2025). "Our data indicate that METTL3 controls SLC7A11 transcription through GATA binding protein 3 (GATA3) and H3K27 lysine demethylase 6B (KDM6B), highlighting a potential approach for cancer therapy by disrupting m6A-regulated ferroptosis in cancer cells." (PMID 39800682, 2025). "As most of our clinical samples came from luminal subtypes carcinomas, we stained for GATA binding protein 3 (GATA3), which is a transcription factor that plays a critical role in the development of epithelial structures in embryonic and adult tissues." (PMID 40470875, 2025). "The commonly used IHC markers to support a diagnosis of a carcinoma of breast primary include mammaglobin, gross cystic disease fluid protein 15 (GCDFP-15), GATA binding protein 3 (GATA3), and SRY-related HMG box 10 (SOX10), in addition to hormone receptors." (PMID 40025593, 2025). "The macrophage infiltration was compared to GATA-3, estrogen receptor (ER), progesterone receptor (PR), human epidermal growth factor receptor 2 (HER-2), and Ki-67 expression in cancer cells." (PMID 36996051, 2023). "MutSigCV analysis identified CDC27, PIK3CA, GATA3, CDH1, CTBP2, and CRIPAK as common cancer driver genes across both Ki67 expression groups (ZF13)." (PMID 37454130, 2023). "Together, these clinical findings are consistent with our results in mice, suggesting an opportunity to use murine systems to further explore how GATA3 regulates FRA1 and c-FOS to control human breast biology as well as cancer development and progression." (PMID 37353480, 2023).
cancer (continued). "GATA3, a zinc-finger transcription factor belonging to the GATA family, has been reported to suppress cancers by regulating their target genes and acts as a master regulator of mammary gland differentiation and homeostasis." (PMID 35804829, 2022). "Of these DEGs, 6 (EGFR, GATA3, DIABLO, CFLAR, RIPK3, and MAPK8) were repressed, while (ZBP1, PLK1, SPATA2, BCL2, ALK, FASLG, TNFRSF21, and LEF1) were upregulated in cancer cases." (PMID 35610275, 2022). "Metastatic cancer cells in the right axilla were also positive for gross cystic disease fluid protein-15 (GCDFP-15) and GATA binding protein 3 (GATA3), suggesting that the metastasis was derived from the breast." (PMID 34920718, 2021). "More directly, our findings provided evidence that the expression of DKK1 was correlated with the level of Th1 markers (STAT1 and IFNG) and Th2 markers (GATA3 and STAT6) in various cancers, such as ACC, KICH, MESO, and PAAD." (PMID 34899842, 2021). "Therefore, GATA3 mutations may play critical roles in migration and invasion of cancer cells but not in initial carcinogenesis." (PMID 33795819, 2021). "We analyzed immune cells (T helper cells, CTLs, Tregs, B-cells, M1- and M2 macrophages), carcinoma cells (pan-cytokeratin, CK5/6, and GATA3) and immune recognition/escape mechanisms (PD-L1 and MHC class I)." (PMID 33863885, 2021). "Among the 16 cross-racial DRGs, all are cancer related according to ICGC and three genes (GATA3, SOX9 and CEBPA) have been regarded as cancer driver genes." (PMID 29745833, 2018). "Among the top 10 DRGs identified for Korean (GSE24375), six genes are GC related (ESRRG, LIMS1, GATA3, GATA6, SOX9, POU2F1) and the other four are cancer related (IRF2, RGS3, MRPL36, FOSB)." (PMID 29745833, 2018). "Although genes like WT1, GATA3 and PHOX2B were frequently hypermethylated in several cancer types, others were restricted to certain tissue types." (PMID 28581523, 2017). "Our study demonstrated that the M and C class changes in an individual cancer driver gene, such as PIK3CA or GATA3, are correlated with opposite histologic changes." (PMID 27283966, 2016). "In the cancer cells, knockdown of p63 or ΔNp63 reduced expression of JAM-A, β-catenin and GATA-3 and knockdown of GATA-3 reduced JAM-A expression." (PMID 27036044, 2016). "Accordingly, MCF7 cells, which heterozygously express GATA3-trunc, display average sensitivity to BIX101294 when compared to a panel of 25 other breast (cancer) cell lines." (PMID 27588951, 2016). "The present study identified GATA3 and GATA5 methylation as a common and cancer-specific event in RCC." (PMID 24549248, 2014). "Transcriptional inactivation and CpG island (CGI) methylation of GATA transcription factor family members GATA3 and GATA5 have been reported for a few types of human cancer." (PMID 24549248, 2014). "Only 2.3% of GATA3-negative cancers had a deletion, and 42.1% of strong GATA3-expressing cancers exhibited high-level amplification." (PMID 39979991, 2025). "Although most carcinomas with GATA3 deletions were negative by GATA3 IHC (92.9%), a GATA3 deletion was only found in 2.3% of 578 GATA3 IHC negative cancers." (PMID 39979991, 2025). "Since METTL3 can negatively regulate the pGL-SLC7A11 promoter reporter, it indicates that transcription factors are also involved in m6A-regulated transcription of SLC7A11.We found that GATA3 is involved in METTL3-regulated expression of SLC7A11 and ferroptosis in cancer cells." (PMID 39800682, 2025).
cancer (continued). "Furthermore, specific demethylation of GATA3 and KDM6B transcripts can increase the expression of SLC7A11, leading to a decrease erastin sensitivity of cancer cells." (PMID 39800682, 2025). "That only 40% of GATA3 high-level amplificated carcinomas showed strong GATA3 immunostaining while 12% were entirely GATA3 negative demonstrates that GATA3 amplification is neither required nor sufficient to induce strong GATA3 expression in these tumors." (PMID 39979991, 2025). "A GATA3 deletion was not seen in any of 539 pTa tumors but it was detectable in 16 (1.1%) of the 1,432 analyzable pT2-4 carcinomas and it was always heterozygous." (PMID 39979991, 2025). "The carcinoma was CK7, CK5/6, P40, and GATA3 positive, favoring a high-grade urothelial carcinoma." (PMID 40125201, 2025). "The complete absence of GATA3 immunostaining in 11 of 95 carcinomas with high-level GATA3 amplification is consistent with data showing that only expressed proteins can be overexpressed in case of gene amplification." (PMID 39979991, 2025). "Overall considering the antioxidant stress and anti-aging functions of BHB target proteins including SOD, GATA3 and SULT2B1, the differences in BHB content may imply cancer cells with various ability to resist surrounding stress." (PMID 38782922, 2024). "There were significant associations between Upk1a, Upk1b and GATA3 immunostaining (p < 0.0001 each), but 11% of GATA3 negative cancers were Upk1a/b positive and 8% of Upk1a/b negative cancers were GATA3 positive." (PMID 37777995, 2024). "The results obtained in this study indicated that GATA-3 expression was higher in benign tumors and well-differentiated carcinomas, showing a positive correlation with ER and a negative correlation with the Ki-67 proliferation marker." (PMID 37483298, 2023). "It has been claimed that myeloid-derived suppressor cells (MDSCs), which are precursors of DCs, macrophages, or granulocytes, have the ability to negatively regulate the immune response in cancer, with a subpopulation of monocytic MDSCs mediated by the EPOR-mediated Jak2/GATA3/STAT3 pathway induced." (PMID 35359375, 2022). "In conclusion, results suggested that high GATA3 expression promoted BLCA to form a non-inflammatory immune TME resistant to cancer immunotherapy." (PMID 35647011, 2022). "Ours is the second largest study that has analyzed the prognostic impact of GATA3 IHC, and it is worth noting that results from the two largest studies confirmed an independent association with the prognosis, even in stratified analyses by cancer subtype, that smaller studies could not detect." (PMID 33800667, 2021). "GATA3 and GATA2 displayed the highest degree of connectivity with 38 and 19 connections, respectively, and KEGG gene enrichment analysis revealed enrichment for immunity functions and processes, and miRNA in cancer terms." (PMID 35201514, 2021). "GATA family of proteins include GATA3 and GATA4 protein, which are deregulated in various cancers." (PMID 36046086, 2021). "Interestingly, some of the transcription factors identified, such as ZNF143 in K562 and GATA3 in MCF-7, play important roles in the relevant cancer types." (PMID 34399797, 2021). "To show the variation in spatial performance, we extracted 422 spots consistent with cancer cells using Visium and compared the number of reads between 46 spots with and 376 spots without GATA3 mutant reads." (PMID 33795819, 2021). "Finally, we stained for basal cytokeratin expression (CK5/6) and luminal characteristics (GATA3) and aligned these with a pan-cytokeratin staining of the carcinoma cells to estimate the proportion of carcinoma cells positive for CK5/6, GATA3 or both." (PMID 33863885, 2021).
cancer (continued). "Following one cycle of carboplatin, paclitaxel +/− veliparib, she had a lower GI bleed, which led to the diagnosis of a cancer of likely intestinal origin (GATA-3-negative)." (PMID 33238387, 2020). "In luminal cancers, the ER-dependent programs are influenced by pioneer factors FOXA1 and GATA3 and thus genes whose promoters contain binding sites or clusters of sites for these factors may be expected to be dependent on ER programs." (PMID 32987805, 2020). "Other notable mutated cancer genes were BRCA2, NF1, and GATA3, each occurring once in non-overlapping tumors." (PMID 31618954, 2019). "Interestingly, all GATA family members besides GATA3 were mostly downregulated in most kinds of cancers, with upregulated vs downregulated study numbers (GATA1 1:7; GATA2 6:39; GATA3 31:36; GATA4 5:18; GATA5 1:17; GATA6 16:37)." (PMID 30872657, 2019). "By analyzing the mRNA expression of LINRIS and GATA3 in human CRC samples (n = 76) from Sun Yat-sen Cancer Center, we also observed a negative correlation between them." (PMID 31791342, 2019). "Reported GATA3 negative rates in metaplastic cancers ranged from 44 to 82%, which was consistent with the 70% (7 out of 10) in the current study." (PMID 31718619, 2019). "To investigate whether STAT6 directly activated GATA3, we overexpressed STAT6 in various cancer cells and observed the upregulation of GATA3 expression." (PMID 30218063, 2018). "Moreover, GATA3 expression is favorable during carcinogenesis as it impedes the EMT and inhibits the metastasis of cancer cells." (PMID 27888801, 2017). "Samples with low or negative levels of YKL-40 exhibited high expressions of both GATA3 and E-cadherin; whereas cancers with high or positive levels of YKL-40 indicated low or negative levels of GATA3 and E-cadherin, P=0.0137 and P=0.0417, respectively." (PMID 21934681, 2011). "Additional proof of HuR involvement with other known cancer genes, such as CD44 and GATA-3, may represent novel insights into the mechanisms of regulation of these cancer targets." (PMID 20370918, 2010). "The GATA family (GATA Binding Protein), which includes GATA2, GATA3, and GATA6, governs critical cellular processes such as cell migration, epithelial-to-mesenchymal transition (EMT), and metastasis, all of which play important roles in cancer formation and progression." (PMID 41155227, 2025). "Further annotation of these cancer cells based on marker gene expression revealed that the non‐proliferating cancer cells could be classified into basal and luminal classes based on the expression of KRT7, marker of basal cells, and GATA3, marker of luminal cells, respectively." (PMID 38582099, 2024). "However, GATA3 positivity was found in 31.5% of 476 Upk1a/Upk1b negative while Upk1a/Upk1b positivity was observed in 42.7% of 569 GATA3 negative pT2-4 cancers." (PMID 37777995, 2024). "However, GATA3 positivity was seen in 53.3% of 261 p63 negative cancers, and p63 positivity was seen in 79.6% of 597 GATA3 negative cancers." (PMID 39539567, 2024). "In contrast, the basal subtype with no GATA3 expression accounts for only 5% of all T1 cancers." (PMID 37629741, 2023). "Furthermore, we evaluated the infiltration level of TIICs in TME of various cancers with the ssGSEA algorithm; results indicated significant negative correlations between GATA3 and most of TIICs, such as activated CD8 T-cells and activated DC cells in BLCA." (PMID 35647011, 2022).
cancer (continued). "The top 15 SGA-FIs connected with CSMD3 and ZFHX4 also form densely connected networks that include well-known cancer drivers, such as KRAS, GATA3, KEAP1, ERBB2 and STK11, suggesting that alteration of CSMD3 and ZFHX4 may perturb some of the same signaling pathways as do these known drivers." (PMID 31276486, 2019). "Indeed, repeating analysis by adding Grade 1 and Grade 2 tumors in the current series showed significant worse survival of GATA3 negative cancer patients (P = 0.0063)." (PMID 31718619, 2019). "Consistent with expectations, canonical luminal genes such as ESR1, GATA3, FOXA1, TFF1 and IGF1R were higher in ER+ samples compared to triple negative samples, while proliferation and mesenchymal genes such as SPRY2, SNAI2, FOSL1, MET and BUB1 were higher in triple negative cancers." (PMID 24520381, 2014). "However, the carcinoma cells were immunopositive for estrogen and progesterone receptors and GATA3 and negative for CDX2, Hep Par 1, and MUC5AC." (PMID 25400965, 2014). "Our quantitative LC-MS/MS data showed no indication of relevantly altered GATA3 levels, which could be explained by IHC-specific confounders (such as more epitope-degraded samples with more advanced, frequently inflamed cancers)." (PMID 38802361, 2024). "All these data indicated that GATA3 was involved in the negative effects of METTL3 on transcription of SLC7A11 and ferroptosis activity of cancer cells." (PMID 39800682, 2025). "PTH, GCM2, SYN, CgA, GATA3, and CAM5.2 are always positive in cancer cells, while TTF1, PAX8, CAL, and TG are always negative." (PMID 38019325, 2023). "In PRC2+-CGI promoters, several known cancer-type-specific TFs were observed, such as FOXM1 in BasalBRCA39 and GATA3 in LumBRCA40; nevertheless, most TFs have not been previously reported in their corresponding cancer types." (PMID 33931649, 2021). "In immunohistochemistry, the cancer cells were immunoreactive for WT1, PAX8, and CA125, and negative for GATA3, mammaglobin, and gross cystic disease fluid protein-15." (PMID 33593410, 2021). "In immunohistochemistry, the cancer cells were immunoreactive for WT1, PAX8, and CA125, and negative for GATA3, mammaglobin, and gross cystic disease fluid protein-15 (GCDFP15)." (PMID 33593410, 2021). "All 10 metaplastic cancers were G3 and 30 and 70% of them were CK7 and GATA3 negative, respectively." (PMID 31718619, 2019). "The significant association of PLAP positivity with biologically relevant molecular features such as p16 alterations, GATA3 and p63 expression represents another argument for a non-random development and a potential functional role of PLAP in positive cancer cells." (PMID 39680294, 2025). "Immunohistochemistry has been performed and revealed that the carcinoma was strongly and diffusely positive for cytokeratin 7 (CK7), GATA-binding protein 3 (GATA3), and p40, and was negative for oestrogen receptor (ER), progesterone receptor (PR), and paired box gene 8 (PAX8)." (PMID 40656261, 2025).